ENSG00000212565
Synonyms: LOC124900395
Gene: Small nucleolar RNA gene on chromosome 17 (48,880,840 to 48,880,967, forward strand). Ensembl gene ENSG00000212565.
Gene Ontology:
Biological process: RNA processing
Cellular component: nucleolus
Homologues: Paralogues in human: SNORA68 (82% identical), SNORA68B (78% identical).